ICAM1 (intercellular adhesion molecule 1)
Diseases named in the same sentence as ICAM1 in open-access papers (continued):
Sharing a sentence is not in itself a finding about the gene and the disease.
asthma (continued). "In the context of IL-33-induced asthma, we found that mice lacking ICAM-1 developed lower AHR and lung inflammation, and confirmed our results using a clinically proven anti-ICAM-1 blocking antibody in Rag−/− mice." (PMID 33193309, 2020). "The addition of LL-37 (2 and 10 μg/ml) in eosinophil cultures did not affect the surface expression of adhesion molecules ICAM-1/CD18 or the release of asthma-related inflammatory IL-6, CXCL8 and CCL4." (PMID 28500314, 2017). "Assessing signal transduction, we observed that the inhibition of Erk1/2 MAPK reduced ICAM1 stimulation by RV in BEC of asthma patients and controls but not COPD patient." (PMID 29182620, 2017). "The asthmatic exacerbation resulted in increased serum levels of IL-6, soluble intercellular adhesion molecule-1 (sICAM)-1 and ECP, and increased concentrations of urinary leukotriene E4 (LTE4) and plasma histamine compared with patients with stable asthma and with the 30 control subjects." (PMID 22966430, 2012). "We showed that the corticosteroid dexamethasone, which has been used in rescue therapy for the treatment of asthma exacerbation, inhibits infection by RV14 by reducing the expression of ICAM-1, the receptor for the major RVs, in human tracheal epithelial cells." (PMID 22966430, 2012). "Together, our findings suggest that modulation of the LFA-1/ICAM-1 molecular pair on ILC2s may represent a promising and unappreciated novel therapeutic strategy regulating trafficking and cytokine production in the context of ILC2-dependent asthma." (PMID 33193309, 2020). "Furthermore, they also demonstrated that VCAM-1, but not E-selectin or ICAM-1, is significantly increased in IL-4-positive asthma patients, compared with IL-4-negative asthma patients." (PMID 29614819, 2018). "However, when the cells were pre-incubated with OM-85 for 48 hours, RV infection dependent expression of ICAM1 was significantly reduced in BEC of asthma and COPD patients, while the effect was not significant in control cells." (PMID 29182620, 2017). "Thus, pro-inflammatory cytokines, inflammatory mediators and substances in the airway mucosa and submucosa, including IL-6, IL-11, ICAM-1, ECP, LTC4, LTD4, and histamine, may induce airway inflammation and smooth muscle contraction in asthma patients with viral infections." (PMID 22966430, 2012). "Thus, in mild asthma, the protection offered by epithelial-derived Type I IFNs towards MCs may outweigh the negative effect of IL-33 on ICAM1 expression and viral entry whereas in severe disease, a lack of epithelial IFNs may render the MCs more vulnerable to infection." (PMID 36366528, 2022). "Again, it was suggested that during an exacerbation of asthma, NK cells expressing ICAM-1 and L-selectin may selectively migrate into inflamed lung tissues or, alternatively, subsets of NK cells that do not express ICAM-1/L-selectin are expanded." (PMID 23801996, 2013).
Obesity (78 papers, 2008 to 2026). Accumulation of substantial excess body fat. "Genes associated with leukocyte migration, such as Alcam, Icam1, Pecam1 and Vcam1, were induced in brain art ECs by sustained obesity." (PMID 36400935, 2022). "In our study, obesity-induced damage to the heart was associated with NF-κB activation and increased in ICAM-1, PECAM-1, TNF-α, IL-1β, and IL-6 expression levels." (PMID 35625374, 2022). "According to the NCEP ATP III and previous studies, there are multiple ASCVD risk factors related to HCL, including overweight/obesity, dyslipidemia, high ICAM1 mRNA expression, and ICAM1 SNPs." (PMID 35282277, 2022). "Separately, in a clinical trial where adults with obesity and risk for insulin resistance consumed a cocoa beverage (vs. a low-flavanol control beverage) for five consecutive days, ICAM-1, IL-6, and C-reactive protein were reduced after a 75-g glucose load." (PMID 32605005, 2020). "Levels of ICAM-1 were associated with obesity (OR = 2.15; 95% CI 1.21–3.82) and MetS (OR = 3.60; 95% CI 1.32–9.84)." (PMID 33299020, 2020). "Mutations of ICAM-1 are associated with different diseases as infarct, biliary atresia, multiple sclerosis, obesity." (PMID 19092999, 2008). "Similarly, plasma ICAM‐1 levels were associated with a worse prognosis on HFpEF51 but our neutrophils' transcriptional studies only detected changes regarding CD11B in an obesity and HFpEF phenotype." (PMID 35818731, 2022). "As for endothelial function, only ICAM-1 levels were associated with the risk of obesity and MetS." (PMID 33299020, 2020). "In humans, obesity is similarly associated with oxidative stress and endothelial activation, as assessed by increased plasma levels of oxidized low-density lipoprotein, C-reactive protein, and soluble forms of ICAM1 and E-selectin." (PMID 31497019, 2019). "Obesity was found to be associated with the elevated s-ICAM-1 levels." (PMID 26981539, 2016). "Serum levels of ICAM-1, E-selectin, P-selectin, L-selectin were higher in patients with type 2 diabetes, and associated with glycemic control, disturbances of lipid metabolism, obesity and insulin resistance." (PMID 26809065, 2016). "Moreover, ICAM1 K469E is associated with obesity and PCOS, according to serum triglyceride levels." (PMID 27965459, 2017). "In conclusion, ICAM-1 positively regulates adipose tissue homeostasis and protects from insulin resistance but promotes liver damage in diet-induced obesity." (PMID 40670579, 2025). "In our experimental model, we found several other circulatory molecules that were increased mainly in the Pso–obesity group, like ICAM-1 and TIMP-1." (PMID 40869018, 2025). "Chronic inflammation in obesity is related to higher neutrophils infiltration on adipose tissue, through interaction between neutrophils-CD11b and adipocytes-intercellular adhesion molecule 1 (ICAM-1) that precede macrophages infiltration." (PMID 38172989, 2024). "Adiponectin acts to prevent vascular dysfunction due to obesity by inhibiting ICAM-1 and VCAM-1 expressions." (PMID 37822716, 2023). "Obesity markers (leptin, neutrophil gelatinase-associated lipocalin (NGAL), retinol-binding protein 4 (RBP4), soluble intercellular adhesion molecule-1 (sICAM-1), and zinc alpha 2-glycoprotein (ZAG))." (PMID 35276788, 2022). "Insulin resistance has been associated with ATM MHC II antigen presentation in murine obesity and in human CD11c+ ATMs, so we examined antigen presentation–related genes HLA-D, CD40, CD80, CD86, and ICAM1 in ATM subtypes." (PMID 34990410, 2022). "Afterward, based on TFEA and qRT-PCR verification, we confirmed that SOCS3, ICAM-1, NT5E, MYC, CCL2, and PPARG were potential ORDEGs that linked obesity and OLF pathogenesis." (PMID 35712246, 2022). "Relative to other brain ECs, art ECs showed enriched expression of several leukocyte adhesion genes, and Vcam1, Pecam1, Alcam and Icam1 were upregulated in art ECs in obesity." (PMID 36400935, 2022).
Obesity (continued). "Other inflammatory markers such as TNF-α, ICAM-1, and E-selectin with a proven relationship with obesity and its complications in adults and adolescents have also not been studied." (PMID 33081030, 2020). "Since some cytokines are secreted by the adipose tissue resulting in the expression of ICAM-1 on endothelial cells, it seems that obesity resulted in the significant relationship between the two variables in their investigation." (PMID 29696063, 2018). "Linear regression was next used to evaluate associations of methylation levels in CRH, ICAM-1, and LINE-1 in relation to the three obesity-related outcomes." (PMID 28360946, 2017). "ICAM -1 is also considered as a marker of endothelial activation and is elevated in a broad array of disease states, including obesity." (PMID 28061787, 2017). "Associated with these changes, obesity increased LFA-1 and ICAM-1 neutrophil expression and altered CXCL1 gradients." (PMID 26956558, 2016). "The serum levels of ICAM-1 are positively correlated with obesity, in particular, to visceral adipose tissue." (PMID 23113882, 2012). "Serum VCAM-1, ICAM-1 and E-selectin concentrations are elevated in obesity, chronic renal failure, in lean and obese subjects genetically predisposed to T2DM and in T2DM." (PMID 20158910, 2010). "Here we show that WD treatment also leads to increased ICAM-1 expression in liver, adipose tissue, colon, and small intestine of WT mice, pointing to an obesity-induced inflammatory status within those tissues and supporting the notion of their joint involvement in MASLD progression." (PMID 40670579, 2025). "Obesity-mediated upregulation of GR that results in increased cortisol sensitivity to ICAM1 downregulation could potentially explain these paradoxical clinical scenarios." (PMID 38396987, 2024). "Cr supplementation decreased the expression of liver nuclear factor kappa-B (NF-κB) p65, and lowered plasma levels of C-reactive protein (CRP), monocyte chemoattractant protein-1 (MCP-1), and intercellular cell adhesion molecule-1 (ICAM-1) in animal models of obesity, metabolic syndrome and T2DM." (PMID 38721033, 2024). "The elevated levels of ICAM-1 and E-selectin were found in children with obesity and adolescents." (PMID 33029514, 2020). "While, ICAM-1 levels were increased in class III obesity group." (PMID 32893859, 2020). "Furthermore, elevated expression of ICAM-1 has been described in the abdominal AT of mice with diet-induced obesity, and in the visceral AT of obese women, in correlation with the expression of the macrophage-related marker CD68 and with BMI." (PMID 31627295, 2019). "ICAM1 expression has been shown to relate with obesity and insulin resistance." (PMID 29273013, 2017). "Therefore, obese AT expresses adhesion molecules including ICAM-1, and may be a potential source of circulating adhesion molecules in obesity." (PMID 31627295, 2019). "In our study, we reveals compatible findings in that, compared to ICAM-1 and VCAM-1, E-selectin is more influenced by obesity." (PMID 31550292, 2019). "Three genes were chosen because they are important regulators of biological pathways involved in obesity: CRH (stress), ICAM-1 (inflammation), and LEP (appetite)." (PMID 28360946, 2017). "Mice lacking ICAM-1 specifically in stromal cells exhibited worsened hyperplastic obesity, showing heightened fatty acid synthesis and lipid storage in adipose tissue, and the related insulin resistance." (PMID 40813463, 2025). "Moreover, dysfunctional HDL-c has proinflammatory effects on the endothelial cells, so we suspected that boys with obesity experience dysfunctional HDL-c, which induced the expression of ICAM-1." (PMID 37822716, 2023). "In fact, older ICAM-1-deficient mice, or even those lacking CD11b/CD18 (one of the main ligands for ICAM-1), have shown an increase in obesity." (PMID 35682832, 2022).
Obesity (continued). "Additionally, animals fed a HFD exhibit high levels of mRNA expression coding ICAM-1 and VCAM-1 adhesion molecules, which are responsible for the recruitment of M1 macrophages to adipose tissue during obesity." (PMID 32774333, 2020). "Both biomarkers are increased in human obesity and are also related, since HMGB-1 induces a proinflammatory change in human microvascular endothelial cells in vitro, characterized by up-regulation of ICAM-1 and production of proinflammatory cytokines." (PMID 28061787, 2017). "In addition to inflammatory mediators like ICAM-1, factors related to extracellular matrix (ECM) components of the adipose tissue have recently emerged as important mediators in obesity-related pathogenesis." (PMID 29273013, 2017). "Noteworthy, no doubts are on the pro-inflammatory role of obesity, with all studies confirming an elevated concentration of EBC IL-6, IL-8 and ICAM-1 in obese than normal weight individuals." (PMID 31461988, 2019). "Our results seem to be consistent with this hypothesis regarding the elevated ICAM-1 levels in class III obesity group, while no statistically significant change in initial stages of obesity (obesity class I and II)." (PMID 32893859, 2020). "In addition, no impairment of CD28, ICAM-1 (CD54) or CCR5 expression was observed, suggesting obesity does not impair the expression of these key receptors involved in Vγ9Vδ2 T cell co-stimulation or homing." (PMID 25785862, 2015). "The adipokines with black lettering are those whose circulating levels are enhanced in obesity and whose total release by adipose tissue explants is enhanced in obesity: IL-6, IL-10, ACE, TGFβ1, ICAM-1, TNFα, IL-1β, PAI-1, and IL-8 that are released by nonfat cells." (PMID 20508843, 2010).
Hypertension (76 papers, 2005 to 2025). The presence of chronic increased pressure in the systemic arterial system. "The elevation of 100 ng/ml ICAM-1 will increase the risk of cardiovascular mortality by 1.10-folds (95% CI (1.05–1.15)) and get worse due to the presence of hypertension and cardiovascular disease." (PMID 37822716, 2023). "Hypertension causes increased release of both ICAM-1 and IL-6; that in turn stimulate CRP release." (PMID 33204538, 2020). "The inflammatory process in hypertension is characterized by increased levels of local inflammatory cytokines such as IL-6, IL-1β, TNF-α, and ICAM-1, which are highly correlated with an increased risk for hypertension, and may be useful diagnostic tools for hypertension in the future." (PMID 33906674, 2021). "Multiple studies have demonstrated that elevated levels of IL-6, ICAM-1, and VCAM-1 are independently associated with incident hypertension, progression of atherosclerosis, and increased cardiovascular events." (PMID 40863231, 2025). "In patients with hypertension, only Neb reduced the oxidative stress-related biomarkers, but both Met and Neb reduced intercellular adhesion molecule-1 (ICAM-1), involved in the recruitment of circulating lymphocytes to the blood vessel wall." (PMID 37998760, 2023). "The level of miR-17, a negative regulator of ICAM1, was decreased in macrophage-derived exosomes obtained from rats with hypertension, and these exosomes elevated the expression levels of ICAM1 and PAI-1 in HCAECs." (PMID 35445015, 2022). "Hcy attained a large effect size, and ICAM-1 attained a moderate effect size when BP groups of hypertension vs. H-type hypertension were compared." (PMID 36547444, 2022). "Leptin injection raised ICAM-1 and Eseltin circulation concentrations, resulting in hypertension and proteinuria in pregnant rats." (PMID 36258174, 2022). "Supplementation with vitamin D in patients with arterial hypertension and type 2 DM was associated with a significant increase in FMD test results and a significant decrease in levels of ox-LDL and ICAM-1 after twelve weeks." (PMID 36141513, 2022). "IL-1β stimulates the expression of vascular cell adhesion protein-1 (VCAM-1), intercellular adhesion molecule 1 (ICAM-1), and E-selectin in essential hypertension patients, which, in turn, results in unwanted atherosclerotic effects." (PMID 33494430, 2021). "Our current study shows that treatment with an HDAC8- 18 selective inhibitor suppresses the increased expression of VCAM-1 and ICAM-1 in Ang II- induced hypertension." (PMID 31223486, 2019). "Correspondingly, in current study, the increased low-grade inflammation in inner of aortae (elevated pro-inflammatory cytokines TNFα, MCP-1, and ICAM-1) underpinned at least some of the pathological basis of the hypertension of the KKAy mice." (PMID 29731737, 2018). "Besides, this plant significantly prevented hypertension and vascular dysfunction in hypertensive rats by inhibiting the secretion of ICAM-1 and the levels of serum endothelin-1 (ET-1)." (PMID 37396948, 2023). "Based on the results of the network analysis and molecular docking, we found that AKT1, VEGFA, eNOS, ICAM-1, PTGS2, and ALB may also be associated with the potential effects of GZD on hypertension." (PMID 33906674, 2021). "Vascular cell adhesion molecule-1 (VCAM-1), intercellular adhesion molecule-1 (ICAM-1), and platelet endothelial cell adhesion molecule (PECAM) may be implicated in hypertension." (PMID 31223486, 2019). "We analyzed the haplotypes of the ICAM-1 gene in those patients with hypertension or smoking." (PMID 25310099, 2014). ", ever smoking with ICAM-1 concentrations (partial R = 0.142 (P = 0.035)), hypertension, diastolic blood pressure, ESR and glucose concentrations with those of E-selection (partial R = 0.176 (P = 0.01), 0.144 (P = 0.037), 0.227 (P = 0.001) and 0.147 (P = 0.036) resp)." (PMID 24453423, 2013).